TREM2 (triggering receptor expressed on myeloid cells 2)
Diseases named in the same sentence as TREM2 in open-access papers (continued):
Sharing a sentence is not in itself a finding about the gene and the disease.
heart failure (5 papers, 2023 to 2025). Inability of the heart to pump blood at an adequate rate to meet tissue metabolic requirements. "Additionally, the implications of TREM2 signaling in macrophages during cardiac injury responses across various heart failure models still require further investigation." (PMID 40083551, 2025). "Some of these MP clusters have been reported in our previous study about human heart failure, such as TREM2+ MPs, proliferation MPs, and MHCII-associated MPs (MHCIIlow and MHCIIint), which indicated that these cell clusters participated in the process of heart failure." (PMID 38185631, 2024). "In human heart failure, single-cell transcriptomic profiling revealed a marked expansion of SPP1+ macrophages, co-expressing markers such as FN1 and TREM2, and occupying fibrotic niches where they orchestrate ECM remodeling through CXCL4 signaling." (PMID 40900730, 2025). "Similar to a recently described population of fibrosis-associated liver macrophages,35SPP1+ macrophages specifically expressed TREM2 and CD9 in both CKD and heart failure." (PMID 36807143, 2023).
leukodystrophy (5 papers, 2021 to 2025). Leukodystrophies are a group of rare, progressive, metabolic, genetic diseases that affect the brain, spinal cord and often the peripheral nerves. "Leukodystrophies related to bi-allelic loss-of-function mutations in CSF1R, TREM2, TYROBP, LRRC33/NRROS or USP18 can be categorized as primary microgliopathies." (PMID 34282843, 2021).
lung adenocarcinoma (5 papers, 2022 to 2025). A carcinoma that arises from the lung and is characterized by the presence of malignant glandular epithelial cells. "Kaplan Meier analysis indicated high TREM2 expression was associated with better overall survival in cervical squamous cell carcinoma, endocervical adenocarcinoma, lymphoid neoplasm diffuse large B-cell lymphoma, lung adenocarcinoma, thyroid carcinoma, and skin cutaneous melanoma." (PMID 36119485, 2022). "TREM2+ TAMs were initially identified by scRNA-Seq in early lung adenocarcinoma patients and can even be detected at the preclinical stage." (PMID 39430099, 2024). "For an exploration of the up-regulated TREM2 in macrophages, we analyzed the single cell RNA sequencing data of human lung adenocarcinoma, and identified TREM2-positive macrophages (TREM2+ M) and TREM2-negative macrophages (TREM2− M)." (PMID 39135069, 2024). "Another more recent study demonstrated high levels of TREM2+ TAMs predicted worse overall survival in both lung adenocarcinoma and lung squamous cell carcinoma, which is also in disagreement with the pan-cancer analysis." (PMID 36119485, 2022). "Further evidence of the tumour‐promoting role of SPP1+ TAMs comes from a murine lung adenocarcinoma model, where a population of TREM2+ macrophages, also expressing the SPP1+ gene signature (TREM2, GPNMB, SPP1, CTSB, RNASE1, GPR183), was identified." (PMID 40395129, 2025). "Novel signature genes of TAMs, including triggering receptor expressed on myeloid cells 2 (TREM2), CD81, macrophage receptor with collagenous structure (MARCO), and apolipoprotein E (APOE), were discovered in lung adenocarcinoma using scRNA-seq." (PMID 36154923, 2022). "In the absence of Trem2, TAM in primary lung adenocarcinoma were unable to express IL18bp, which normally intercepts IL-18 and prevents IL-18-dependent activation of NK cells." (PMID 39430099, 2024).
osteoporosis (5 papers, 2021 to 2025). A condition of reduced bone mass, with decreased cortical thickness and a decrease in the number and size of the trabeculae of cancellous bone (but normal chemical composition), resulting in increased fracture incidence. "The link between the TREM2 variant, AD, and osteoporosis provides a promising avenue for future research, potentially paving the way for novel therapeutic strategies targeting neuroinflammation in AD." (PMID 38334917, 2024). "In addition, AD and osteoporosis both utilize the Wnt/β-catenin signaling pathway, have impairments in angiogenesis, and are associated with the common genetic variant of TREM2, R47H, which can exacerbate neuroinflammation." (PMID 38334917, 2024). "Understanding the role of osteoclasts in the bone phenotype in NHD is yet to be elucidated while TREM2/DAP12 pathway is an attractive target for treatment of osteoporosis." (PMID 33568650, 2021). "A recent study found that female carriers of the TREM2 variant exhibited lower bone density compared to non-carriers, suggesting a potential link between AD and osteoporosis." (PMID 38334917, 2024). "For individuals with osteoporosis, preemptive genotyping for TREM2/DAP12, CSF1, CCR5, and Pyk2 signaling pathways could suggest relative risks for AD compared to population norm with a matched genetic background." (PMID 33568650, 2021).
renal fibrosis (5 papers, 2021 to 2026). A final common manifestation of a wide variety of chronic kidney diseases characterized by glomerulosclerosis and tubulointerstitial fibrosis. "Using Trem2‐deficient mice, we showed that knockout of Trem2 mitigated renal macrophages from properly regulating renal inflammation, which led to increased renal fibrosis in vivo." (PMID 40000418, 2025). "RNA‐seq data suggested that the loss of Trem2 expression resulted in the pronounced upregulation of the IL‐6 family member Lif, which reportedly alleviates myocardial and renal fibrosis." (PMID 39350473, 2024). "In conclusion, TREM2 promotes renal fibrosis by activating β-catenin signalling to drive profibrotic M2 macrophage responses, establishing TREM2 blockade as a therapeutic strategy for obstructive nephropathy." (PMID 41795142, 2026). "Separately, TREM2 inhibitory peptide sequence IA9 administration reduced renal fibrosis and M2 polarisation in UUO mice." (PMID 41795142, 2026). "Urinary TREM-1/TREM-2 ratio was a potential biomarker for the diagnosis of renal fibrosis in CKD patients." (PMID 34176389, 2021). "This study investigated TREM2's role in macrophage polarisation and renal fibrosis progression." (PMID 41795142, 2026). "Obstructive nephropathy leads to renal fibrosis, and Triggering Receptor Expressed on Myeloid Cells 2 (TREM2) drives this macrophage-mediated process, but its mechanism remains unclear." (PMID 41795142, 2026). "In renal fibrosis, the expression of TREM-2 in kidney tissue may have differences compared to healthy control." (PMID 34176389, 2021). "In summary, our study demonstrated that the urinary TREM-1/TREM-2 ratio could well predict renal fibrosis severity in CKD, which suggested this will serve as a novel independent non-invasive biomarker to monitor the progression of kidney fibrosis in CKD." (PMID 34176389, 2021). "Accordingly, this study was designed to determine the expression of urinary TREM-1 and TREM-2 via qPCR indicate CKD and renal fibrosis." (PMID 34176389, 2021). "Urinary TREM-1 and TREM-2 mRNA detection and the TREM-1/TREM-2 ratio served as a non-invasive biomarker of renal fibrosis." (PMID 34176389, 2021). "If the urinary mRNA expression of TREM-1 and TREM-2 have correlated with CKD and renal fibrosis was still unknown." (PMID 34176389, 2021). "In our data, we found that in none-mild renal fibrosis human kidney tissue, the expression of TREM-1 was higher than TREM-2." (PMID 34176389, 2021). "Our study firstly indicated that the mRNA ratio of urinary TREM-1/TREM-2 was related to CKD and may serve as a potential non-invasive biomarker of renal fibrosis." (PMID 34176389, 2021). "However, the role of TREM-2 in CKD and renal fibrosis has not been further studied." (PMID 34176389, 2021).
rheumatoid arthritis (5 papers, 2020 to 2026). A chronic, systemic autoimmune disorder characterized by inflammation in the synovial membranes and articular surfaces. "In rheumatoid arthritis (RA), a reduction in TREM2+ tissue-resident macrophages is often observed, impairing phagocytic clearance and bone homeostasis, thereby exacerbating disease progression." (PMID 41050649, 2025). "Another study revealed that TREM2 inhibited the activation of TNF-α-induced inflammation response in rheumatoid arthritis via the p38 pathway." (PMID 32617097, 2020). "More recent studies using healthy and rheumatoid arthritis (RA) synovium have proposed new nomenclature for different synovial macrophage subsets, including CX3CR1+/TREM2+ lining macrophages and subsets based on the expression of CD163, CD206, and MERTK." (PMID 37612718, 2023).
schizophrenia (5 papers, 2015 to 2024). A major psychotic disorder characterized by abnormalities in the perception or expression of reality. "In the present study, we report gene expression and association analyses of both TYROBP and TREM2 in patients with AD and schizophrenia." (PMID 26332043, 2015). "Higher TREM2 mRNA levels in leukocytes of schizophrenia may be associated with peripheral inflammation or microglial involvement." (PMID 26332043, 2015). "In the present study, we found that TREM2 was more highly expressed in leukocytes of patients with AD and schizophrenia, which were of different disease and age groups, whereas TYROBP expression was not altered in these groups." (PMID 26332043, 2015). "We believe that our study is an important first step in understanding the role of TREM2 in the pathophysiology of AD and schizophrenia." (PMID 26332043, 2015). "In contrast, TREM2 expression was significantly higher in patients with AD and schizophrenia compared to that in their respective controls (P < 0.001 in both cases)." (PMID 26332043, 2015). "The objective of this study was to reveal the involvement of TYROBP and TREM2 in the pathophysiology of AD and schizophrenia." (PMID 26332043, 2015). "We performed genotyping of 3 tag SNPs (rs8113524 and rs3817624 in TYROBP and rs2234256 in TREM2) in 796 patients with schizophrenia and 510 controls (unrelated Japanese participants)." (PMID 26332043, 2015). "Surprisingly, TREM2 mRNA expression was also elevated in patients with schizophrenia." (PMID 26332043, 2015). "In conclusion, we report for the first time that TREM2 expression in leukocytes is elevated not only in AD but also in schizophrenia and may be a clinical biomarker for these diseases." (PMID 26332043, 2015). "To date, this is the first report showing TREM2 upregulation in schizophrenia." (PMID 26332043, 2015). "Inflammatory processes involving TREM2 may occur in schizophrenia, as observed in neurocognitive disorders such as AD." (PMID 26332043, 2015). "Because inflammation in glial cells may lead to neuronal changes in schizophrenia, TREM2 expression in brain samples of patients with schizophrenia should be studied in the future." (PMID 26332043, 2015). "We could not find significant association between TYROBP and TREM2 gene polymorphisms and schizophrenia." (PMID 26332043, 2015). "Therefore, higher level of TREM2 mRNA in AD and schizophrenia in this study may not be caused by gene polymorphisms but by other factors such as epigenetic modification." (PMID 26332043, 2015). "Although a vast amount of clinical data has strongly implicated the role of inflammatory and degenerative processes in the pathophysiology of schizophrenia, TREM2 expression in schizophrenia has not yet been examined." (PMID 26332043, 2015).
synucleinopathies (5 papers, 2019 to 2025). "In synucleinopathy models, both in vivo and in vitro studies showed that TREM2 deficiency increases microglia activation during α-syn-induced inflammatory processes, leading to an increased loss of dopaminergic neurons (53% vs. 28% after 3 weeks) in animal models." (PMID 40309835, 2025). "TREM2 R47H AD patients demonstrated a shortened course of the disease, pronounced synucleinopathy, changed microglial morphology, and decreased level of the microglial marker Iba1, suggesting that compromised TREM2 signaling has a strong effect on microglia function in the disease." (PMID 33101276, 2020). "This could support the hypothesis that TREM2 is elevated in synucleinopathies in contrast to YKL-40." (PMID 31127154, 2019). "Targeting TREM2 and AEP could point to a new therapeutic approach for synucleinopathies, including PD." (PMID 39665233, 2025).
tuberculosis (5 papers, 2022 to 2026). A chronic, recurrent infection caused by the bacterium Mycobacterium tuberculosis. "Here, we show that Mycobacterium tuberculosis, the causative agent for tuberculosis, specifically binds to human TREM2 to disable the macrophage antibacterial response." (PMID 35924849, 2022). "TREM2 and CD163 are highly expressed in tuberculous granulomas and may be associated with the formation of tuberculosis lesions and latent infections." (PMID 40242752, 2025). "As such, targeting TREM2 signaling could prove to be a potential therapeutic strategy against tuberculosis." (PMID 35924849, 2022).
acute myeloid leukemia (4 papers, 2024 to 2025). Acute myeloid leukemia (AML) is a group of neoplasms arising from precursor cells committed to the myeloid cell-line differentiation. "Besides, in acute myeloid leukemia (AML), TREM2, as a novel receptor for IL-34, can induce myeloid differentiation and inhibit AML progression by inhibiting the ERK1/2/Rasal3 signaling pathway." (PMID 38725629, 2024).
cerebral infarct (4 papers, 2019 to 2024). "The results of this study suggest that Trem2 can be a therapeutic target for patients with cerebral infarction." (PMID 38348100, 2024). "Trem2 has been shown to be primarily expressed in microglia, which are known to play an important role in ameliorating the progression of cerebral infarction." (PMID 38348100, 2024). "This study highlighted the regulatory role of Casp8, Gsdmd and Trem2 in pyroptosis, underscoring their potential impact on cerebral infarction." (PMID 38348100, 2024). "Taken together, pyroptosis-related genes Casp8, Gsdmd, and Trem2 exhibited higher expression levels in the brain tissues of mice with cerebral infarction." (PMID 38348100, 2024). "Pyroptosis-related genes Casp8, Gsdmd and Trem2 were screened out in cerebral infarction by bioinformatics, and they were verified to be highly expressed in cerebral infarction." (PMID 38348100, 2024). "Casp8, Gsdmd and Trem2 can regulate pyroptosis, thus affecting cerebral infarction." (PMID 38348100, 2024). "Therefore, we conclude that Trem2 is a protective factor that regulates pyroptosis, thus impacting the progression of cerebral infarction." (PMID 38348100, 2024). "In addition, we constructed a mouse MCAO model through animal experiments, and confirmed the high expression of pyroptosis-related genes Casp8, Gsdmd and Trem2 in the brain tissues of mice with cerebral infarction." (PMID 38348100, 2024). "In addition, the high expression of Casp8, Gsdmd and Trem2 in mice with cerebral infarction was confirmed by animal experiments." (PMID 38348100, 2024). "Therefore, Trem2 is a protective factor regulating pyroptosis, thus influencing the progression of cerebral infarction." (PMID 38348100, 2024). "At the cellular level, Trem2 was confirmed to regulate the pyroptosis of BV2 cells, thereby affecting the progression of cerebral infarction." (PMID 38348100, 2024). "In line with the findings in vitro, cyclocreatine administration could decrease the number of apoptotic neurons, and alleviate cerebral infarction and demyelination, as well as promoting the proportion of IGF1+ microglia, even in Trem2–/– mice." (PMID 38151703, 2024).
cholestasis (4 papers, 2021 to 2025). Impairment of the bile flow caused by obstruction within the liver, or outside the liver in the bile duct system. "In an animal experiment, antibiotic treatment partially eliminated increased cholestasis observed in triggering receptor expressed on myeloid cells-2 (TREM-2)-deficient mice after bile duct ligation (BDL)." (PMID 37242293, 2023).
chronic kidney disease (4 papers, 2021 to 2025). Impairment of the renal function secondary to chronic kidney damage persisting for three or more months. "An adoptive cell therapy using Triggering Receptor Expressed on Myeloid Cells 2 (TREM2)‐overexpressing macrophages effectively mitigates the transition from acute kidney injury (AKI) to chronic kidney disease (CKD) in UIRI animals." (PMID 40000418, 2025). "Additionally, the expression of TREM2 within nephritis DCs catalyzes the production of nitric oxide (NO), which subsequently inhibits the differentiation of Th17 cells and mitigates the progression of chronic kidney disease (CKD)." (PMID 40552184, 2025).
clear cell renal carcinoma (4 papers, 2022 to 2025). A malignant epithelial neoplasm of the kidney characterized by the presence of lipid-containing clear cells within a vascular network. "In clear cell renal carcinoma (ccRCC) patients, TREM2+ TAMs were defined by the expression of TREM2, APOE, and C1QA-C, along with other macrophage markers associated with immunosuppression, such as LILRB5, MERTK, STAB1, and IGF1." (PMID 35746551, 2022). "TREM2+ macrophages have been found to accumulate in human tumors, with infiltration of TREM2/APOE/C1Q expressing macrophages serving as a potential biomarker for disease recurrence in clear cell renal carcinoma." (PMID 39811671, 2025).
delirium (4 papers, 2022 to 2025). A disorder characterized by confusion; inattentiveness; disorientation; illusions; hallucinations; agitation; and in some instances autonomic nervous system overactivity. "LM‐ and AS‐induced delirium led to microglial activation in the hippocampus as evidenced by up‐regulation of microglial activation‐related genes (such as Il6ra, Tyrobp, Cd68, Aif1, Csf1r, and Trem2) and of relevant inflammatory factors (such as Il‐1β, Tnfα, Ccl2, Ccl5, and Ccl8)." (PMID 35713240, 2022).
diffuse large B-cell lymphoma (4 papers, 2021 to 2025). "In diffuse large B-cell lymphoma (DLBCL), the expression of TREM2 on M-MDSCs has been found to be associated with immunosuppressive functions, potentially by upregulating the expression of Arginase 1 (ARG1) to inhibit the proliferation of CD8+ T cells, thereby promoting tumor growth." (PMID 40242752, 2025).
esophageal cancer (4 papers, 2018 to 2024). A primary or metastatic malignant neoplasm involving the esophagus. "TREM2 is highly expressed in esophageal carcinoma cells and directly maintains their survival." (PMID 38910324, 2024).
esophageal squamous cell carcinoma (4 papers, 2019 to 2025). Esophageal squamous cell carcinoma (ESCC) is a type of esophageal carcinoma (EC) that can affect any part of the esophagus, but is usually located in the upper or middle third. "Notably, a prior scRNA-seq analysis indicated that TREM2+ TAMs were significantly enriched in esophageal squamous cell carcinoma (ESCC) tumor tissues and were closely associated with shorter OS in patients with ESCC." (PMID 40242752, 2025). "We analyzed two single-cell RNA sequencing (scRNA-seq) datasets (GSE145370 and GSE160269) of esophageal squamous cell carcinoma to identify a novel TREM2-positive TAM subpopulation characterized by upregulation of TREM2, C1QC, C1QB, C1QA, SPP1, and APOE." (PMID 37187751, 2023).
glaucoma (4 papers, 2020 to 2024). Increased pressure in the eyeball due to obstruction of the outflow of aqueous humor. "We also investigated the association between glaucoma and TREM2, a transmembrane receptor expressed by myeloid cells that has recently been associated with AD." (PMID 32614373, 2020). "Manipulating TYROBP and TREM2 is a promising strategy to define functions of microglia in glaucoma and a possible avenue for treatment." (PMID 32450896, 2020). "–25 Given that microglia have also been implicated in the pathogenesis of glaucoma and that APOE is upregulated in the retina and the aqueous humor of patients with glaucoma, we hypothesized that APOE and TREM2 may have genetic associations with POAG as well." (PMID 32614373, 2020). "Therefore, TREM2-dependent microglia responses may differ between glaucoma and AD, but this requires further investigation." (PMID 39015474, 2024).